LEP (leptin)
Diseases named in the same sentence as LEP in open-access papers (continued):
Sharing a sentence is not in itself a finding about the gene and the disease.
COVID-19 (continued). "In this scenario, the aim of this study was to investigate the serum levels of adiponectin, its HMW oligomers, leptin, and resistin in severe COVID-19 patients, focusing on their correlation with clinical and biochemical patient parameters." (PMID 36674646, 2023). "Our results show that, even after adjusting for BMI, sex, and age, leptin transcript levels remained significantly higher in WAT of COVID-19 cases compared to controls." (PMID 37246981, 2023). "A large, observational study on healthy patients and patients with COVID-19 divided into two groups according to COVID-19 severity (moderate and severe) showed a reduced adiponectin to leptin ratio which is a marker of adipose tissue dysfunction." (PMID 37240656, 2023). "Mainly, the MVPA covariate adjusted IL-10, triglycerides, and leptin in the plasma of post- COVID-19 patients." (PMID 37753077, 2023). "Our previous study found that plasma leptin levels were increased in critical COVID-19 patients compared to non-COVID-19 critical patients." (PMID 36509969, 2023). "We did not identify a direct positive relationship between the levels of leptin and IL-6 in hospitalized COVID-19 patients." (PMID 36509969, 2023). "We found interesting data regarding a higher fat mass (%) with worsened leptin parameters in the post-COVID-19 group compared with control; however, this result is associated with the level of physical activity, since it disappeared after adjustment by MVPA." (PMID 37753077, 2023). "In a study on 31 COVID-19 patients, the serum leptin levels of mechanically ventilated patients were significantly higher in comparison with the control group." (PMID 37240656, 2023). "Proinflammatory adipokines such as leptin are upregulated, while anti-inflammatory adipokines such as adiponectin are downregulated in severe COVID-19." (PMID 37763674, 2023). "Patients with COVID-19 typically have higher levels of leptin, TNF-∝, interleukin-1, interleukin-2 and interferon-gamma but lower levels of helper T cells, cytotoxic T cells, regulatory T cells and natural killer (NK) cells (IFN-∝)." (PMID 37297724, 2023). "In the subgroup with BMI between 25 and 30, leptin was 6278 pg/mL (915–9857) in the control group and 9336.94 pg/mL (3864–12024) in the COVID-19 group (p=0.03)." (PMID 35529082, 2022). "Leptin’s effect on neutrophils is especially important in COVID-19 progression in the obese state: increased leptin levels, characterized by increased neutrophilic lung inflammation, causes more severe lung injury." (PMID 35795152, 2022). "Several studies have shown that COVID-19 in obese people can lead to significant behavioral changes in adipokines (increase in leptin, decrease in adiponectin, increase in resistin, and decrease in omentin)." (PMID 36497720, 2022). "In the subgroup of patients with BMI >30, leptin was 8764.32 pg/mL (1932–11115) in the control group and 10900 pg/mL (3905–17193) in the COVID-19 group (p=0.01)." (PMID 35529082, 2022). "In particular, in the subgroup with BMI <25, leptin was 2841 pg/mL (1750–9465) in the control group and 3790 pg/mL (1869–10900) in the COVID-19 group (p=0.31)." (PMID 35529082, 2022). "Leptin activates monocytes promoting cytokine storm that contribute to severe respiratory distress syndrome and multiple-organ failure in COVID-19." (PMID 35002761, 2021). "In a recent cross-sectional study in 31 COVID-19–positive patients, interestingly, the serum leptin levels of ventilated patients were significantly higher compared with the control groups." (PMID 34220807, 2021). "Among patients with COVID-19, leptin was significantly higher (p < 0.001) in females (22.9 ng × mL−1; IQR (Q3–Q1) = 29.8) as compared to males (17.5 ng × mL−1; IQR (Q3–Q1) = 29.9)." (PMID 35052684, 2021). "In a cross-sectional study, COVID-19 patients displayed significantly increased leptin levels: the mean serum leptin level was 21.2 ug/L vs. 5.6 ug/L for COVID-19 patients and controls respectively." (PMID 33995281, 2021).
COVID-19 (continued). "Of note, leptin levels are increased in patients with COVID-19 compared with controls as well as in severe patients with COVID-19 compared with mild patients." (PMID 35002761, 2021). "Leptin was higher at ICU admission in patients with COVID-19 as compared to blood donors, serving as controls." (PMID 35052684, 2021). "Usually, patients who have COVID-19 have a decreased number of helper T cells, cytotoxic T cells, regulatory T cells, and natural killer (NK) cells, but increased leptin, TNF-α, interleukin-1 (IL-1), interleukin-2 (IL-2), and interferon-gamma (IFN-γ)." (PMID 34064950, 2021). "Leptin modulation of inflammatory responses can directly contribute to the pathophysiology of COVID-19." (PMID 35002761, 2021). "Using a cytokine array chip containing 174 proteins Wang and co-workers found that overweight COVID-19 patients were more likely to have high levels of leptin." (PMID 35052684, 2021). "They noted that leptin was higher in patients with COVID-19 and that there was a connection between the leptin levels and the progress of the disease." (PMID 35052684, 2021). "Leptin levels were significantly higher in patients with COVID-19 (18.3 ng × mL−1; IQR = 30.4), than in healthy controls (7.8 ng × mL−1; IQR = 6.4)." (PMID 35052684, 2021). "Median leptin level in plasma was significantly (p < 0.001) higher at ICU admission in COVID-19 patients (18.3 ng × mL−1; IQR (Q3–Q1) = 30.4), compared to healthy controls (7.8 ng × mL−1; IQR (Q3–Q1) = 6.4)." (PMID 35052684, 2021). "We observed dramatically decreased protein levels of protein tyrosine phosphatase receptor type C, leptin, and tartrate-resistant acid phosphatase type 5, which are involved in lymphopenia, and platelet basic protein in COVID-19 patients." (PMID 33203833, 2020). "The presented results, although derived from a small sample size, support the idea that the leptin–adiponectin ratio was elevated in patients with COVID-19 with MetS." (PMID 33328246, 2020). "It has been postulated that leptin, which regulates both appetite and immunity, may contribute to the pathogenesis of COVID-19." (PMID 40650217, 2025). "Given its multifaceted roles in the immune system, leptin’s involvement may significantly shape the pathophysiology of COVID-19 by influencing monocyte signaling and inflammatory reactions." (PMID 39062978, 2024). "Leptin was lower in the placenta and colostrum of mothers who suffered COVID-19, and this could have important implications for fetal lung development because this protein hormone modulates fetal respiratory health through pleiotropic actions." (PMID 38610889, 2024). "This diabetogenic effect of COVID-19 may have been due to beta cell dysfunction, disturbance of adiponectin/leptin level that can dysregulate the glucose level, and systemic inflammation." (PMID 39062154, 2024). "Interestingly, severe COVID-19 patients with a high BMI had higher levels of plasma leptin than critical COVID-19 patients with a similarly high BMI, respectively 16.2 ng/ml vs 6.3 ng/ml, p = 0.017." (PMID 36509969, 2023). "Similarly, convalescent COVID-19 children also exhibited higher levels of Adipsin and Leptin in comparison to control children." (PMID 37013538, 2023). "Hence, this study aims to examine the association between circulating leptin and adiponectin and the severity and mortality of SARS-CoV-2 infection in a cohort of patients hospitalized with COVID-19." (PMID 36960389, 2023). "However, patients with severe COVID-19 were also reported to have approximately 3-fold higher serum leptin levels compared to critical COVID-19 patients." (PMID 37238973, 2023). "Implying that Leptin levels are reduced in critically ill COVID-19 patients who have a high BMI." (PMID 36509969, 2023).
COVID-19 (continued). "When we address the hormones and metabolic profile related with energy metabolism, we may observe that leptin, triglycerides, and leptin/VAT ratio parameters were higher in the post-COVID-19 group when compared with the control group, adjusted for MVPA." (PMID 37753077, 2023). "These risk factors are also associated with adipose tissue dysfunction and could have influenced the expression of BDNF, adiponectin, and leptin even before the onset of COVID-19 in the studied patients." (PMID 37408184, 2023). "Similarly, convalescent COVID-19 children had elevated levels of adipsin, leptin, insulin, C-peptide, glucagon, ghrelin and Glucagon-like peptide-1 (GLP-1) in comparison to control children." (PMID 37013538, 2023). "This suggests that leptin plays only a limited role in the pathogenesis of COVID-19." (PMID 36960389, 2023). "Studies have shown leptin levels could predict disease severity and significantly correlate with decreased lymphocyte count and disease progression in severe COVID-19 individuals." (PMID 37408184, 2023). "These facts certainly caused heterogeneities in how COVID-19 patients would appear in the ICU admission; therefore, leptin levels could also be the collected data." (PMID 37408184, 2023). "Likewise, in a cohort of 195 hospitalized COVID-19 patients plasma leptin levels remained rather constant during hospital stay and were not related to inflammation or clinical outcomes." (PMID 37238973, 2023). "Alternatively, reduced adiponectin and increased leptin serum concentrations as surrogates of chronic inflammation may reflect metabolic disease which per se impacts the course of COVID-19." (PMID 36788324, 2023). "Severe COVID-19 cases are characterized by high levels of circulating leptin." (PMID 37246981, 2023). "Similarly, monitoring COVID-19 patients over time in a cohort in Brazil, leptin levels were unrelated to disease severity and mortality." (PMID 37238973, 2023). "Nevertheless, several studies support a trend towards elevated leptin levels in COVID-19 patients." (PMID 37238973, 2023). "In line with this hypothesis, recent small studies from our group and others identified that plasma leptin was increased in COVID-19 patients admitted to the ICU." (PMID 36509969, 2023). "The results showed that increased adiponectin and reduced leptin or the rise in adiponectin/leptin ratio could be related to the inflammatory burden in COVID-19 and its mortality, principally in pre-existing cardiometabolic diseased patients." (PMID 37408184, 2023). "In line with this hypothesis, recent studies found plasma leptin to be increased in COVID-19 patients admitted to the intensive care." (PMID 35837388, 2022). "It was recently hypothesized that dysregulated leptin levels may compromise the immune system in COVID-19 patients and worsen the outcomes of the infection." (PMID 35268057, 2022). "Overweight patients with COVID-19 tended to have higher leptin levels, which further activated monocytes, leading to amplification or imbalance of immune response, which may also be the mechanism of overweight patients more prone to serious diseases." (PMID 34996987, 2022). "Moreover, we and others reported before that plasma leptin levels are increased in critically ill COVID-19 patients." (PMID 35837388, 2022). "Leptin correlated with monocyte M1 (inflammatory) polarization in COVID-19 patients and mechanistic experiments revealed that leptin activated STAT3/NF-κB signaling and promoted M1-polarization marker gene and TLR gene expression in immortalized monocyte THP-1 cells." (PMID 33804765, 2021). "This raised our curiosity whether leptin could influence the clinical course in COVID-19 and, hence, be an independent predictor of outcome." (PMID 35052684, 2021). "The gender-associated difference, which we observed in plasma leptin levels, has so far not been described in COVID-19 patients." (PMID 35052684, 2021).
COVID-19 (continued). "Excessive adipose tissue and high circulating levels of leptin may contribute to severe progression of COVID-19 and to development of respiratory failure and ARDS." (PMID 33824998, 2021). "It has been suggested that leptin could be involved in the etiology of several effects commonly observed in patients with COVID-19." (PMID 35002761, 2021). "Thus, we have no knowledge on any change in plasma leptin levels during the course of COVID-19 or different levels of leptin between these two different cohorts." (PMID 35052684, 2021). "This review aimed to summarize the available evidence about: (i) the role of leptin in immune modulation; (ii) the role of gut microbiota within the gut-lung axis in modulating leptin sensitivity; and (iii) the role of leptin in the pathophysiology of COVID-19." (PMID 35002761, 2021). "Based on these observations, the hypothesis was mounted that high leptin levels support development of a cytokine storm and (pharmacological) interference with leptin production might be considered a possible treatment of COVID-19." (PMID 33824998, 2021). "SERPINA5 and leptin showed the greatest downregulation as COVID-19 severity increased." (PMID 33704068, 2021). "Furthermore, there is a mismatch in the quote between the anti-inflammatory adiponectin and the pro-inflammatory leptin in COVID-19 patients grouped depending on the severity of their disease." (PMID 35052684, 2021). "Median plasma leptin level in COVID-19 patients living 30 days after ICU admission was 20.3 ng × mL−1 (IQR = (Q3–Q1) = 32.1), whereas those who died within 30 days after ICU admission had median plasma leptin level at 16.7 ng × mL−1 (IQR = (Q3–Q1) = 23.6) (n.s.)." (PMID 35052684, 2021). "COVID-19 has worse outcomes in the obese and diabetic populations, likely because these patients are already in a proinflammatory state at baseline due to elevated levels of interleukin 6 (IL-6) from insulin and leptin resistance." (PMID 32708430, 2020). "The combination of increased ACE-2R on adipocytes along with elevated levels of insulin, leptin, and acyl moieties allows COVID-19 to create the perfect “cytokine storm” leading to severe ROS formation which destroys mitochondria, especially in patients with abundant white fat cells." (PMID 32708430, 2020). "In patients with pneumonia, leptin is inversely correlated with biomarkers of inflammation, a result that could be correlated with the pro-inflammatory state in mothers suffering from COVID-19." (PMID 38610889, 2024). "The adiponectin/leptin ratio was found to be induced in patients with moderate COVID-19, suggesting unbalanced levels of these adipokines may play a role in patients with moderate and severe COVID-19." (PMID 38791005, 2024). "Additionally, resveratrol reduced AT leptin expression, which may exert favorable impacts on the outcome of COVID-19." (PMID 38390861, 2024). "Furthermore, the adiponectin/leptin ratio of COVID-19 patients is low, and may serve as a tool to predict admission to intensive care and death." (PMID 37238973, 2023). "The crucial question is whether or not the cytokine storm in COVID-19 patients is linked to leptin dysregulation." (PMID 37240656, 2023). "However, leptin was shown to induce expression of resistin and galectin-3, and thereby may contribute to higher levels of resistin and galectin-3 in the serum of COVID-19 patients." (PMID 37238973, 2023). "Therefore, we can hypothesize that leptin can also contribute to neutrophils’ infiltration in airways and in other tissues during COVID-19, which also contribute to worsen prognosis in obese individuals." (PMID 33816341, 2021). "Therefore, it could even be argued that defective LEP signalling could be protective against the pro-inflammatory phenotype of COVID-19." (PMID 33512658, 2021). "We investigated the effect of BMI on leptin, JAK2 and lymphocyte percentage and their effect on COVID-19 severity." (PMID 41359762, 2025).
COVID-19 (continued). "With regard to colostrum, adiponectin, resistin, and insulin concentrations showed an increase, while a decrease in GLP-1, leptin, and PYY was also reported in the colostrum of mothers suffering from COVID-19 compared with the control group." (PMID 38610889, 2024). "Notably, adipose mass emerges as a determinant for the severe prognosis of COVID-19, suggesting that the association with leptin may manifest as a secondary rather than a direct relationship." (PMID 38396763, 2024). "As for adiponectin, resistin, and insulin, their concentrations showed an increase; a decrease in GLP-1, leptin, and PYY was also reported in the colostrum of mothers suffering from COVID-19 compared with the control group." (PMID 38610889, 2024). "On the other hand, a decrease in GLP-1 (p < 0.05), leptin (p < 0.05), and PYY (p < 0.01) was reported in the colostrum of mothers suffering from COVID-19 compared with the control group." (PMID 38610889, 2024). "Further research is imperative to elucidate the intricate role of visfatin and leptin in SARS-CoV-2 infection and their potential as biomarkers for COVID-19 severity and prognosis." (PMID 39200926, 2024). "Endocrine-specific genes (e.g., HSD3B2, INS, IAPP, TSHR, FOXE1, LEP, and CRYGD) were deregulated in COVID-19 cases in an organ-specific manner." (PMID 37246981, 2023). "We measured the adipocytokines levels (Adipokines, Adipsin, Resistin, Leptin, Visfatin and Plasminogen Activator Inhibitor-1 (PAI-1)) in acute, convalescent COVID-19 and control children." (PMID 37013538, 2023). "Moreover, leptin was overexpressed in human bronchial epithelial cells during viral infection, which in addition to other immune alterations might justify the higher circulating leptin levels in ventilated patients with COVID-19 than control groups." (PMID 37217748, 2023). "In contrast, leptin was increased in COVID-19 patients with ARDS, resulting in adiponectin-to-leptin ratios that would support AT dysfunction in IR." (PMID 36992767, 2022). "Since very little is known about leptin in severe viral infections and the picture is hazy, future studies within this field may focus not only on progressive evaluation of adipokines during the course of COVID-19 but may also pay attention to subgroup analyses." (PMID 35052684, 2021). "Therefore, it seems that, upon infection, patients with excessive fat mass are prone to produce more leptin, which in turn activates monocytes promoting that cytokine storm that has been recognized to contribute to severe respiratory distress syndrome and multiple-organ failure in COVID-19." (PMID 35002761, 2021). "The total mortality rate in COVID-19 at 30 days after ICU admission was 23% and ROC for leptin was 0.55." (PMID 35052684, 2021). "Plasma leptin was analyzed in 222 out of 229 patients with severe COVID-19 on admission to an ICU at Uppsala University Hospital, a tertiary care hospital in Sweden, and compared to plasma leptin in 25 healthy blood donors." (PMID 35052684, 2021). "Despite its known pro-inflammatory effects, we were again unable to find any statistical evidence of a mediating role of leptin in the relationship between BMI and COVID-19 severity and to our knowledge no published study has reported this effect." (PMID 41359762, 2025). "The increased WAT inflammation seen in COVID-19 patients and the relationship between increased levels of the WAT-derived adipokine leptin and lung dysfunction suggests that WAT itself may play a role in the effects of obesity on COVID-19 severity." (PMID 40027795, 2025). "A prospective observational study reported that high concentrations of resistin were associated with worse clinical outcomes and more pronounced inflammation in COVID-19 patients, while leptin and adiponectin were not." (PMID 39469144, 2024). "Recent researchers showed, regardless of normal-weight and obese women of COVID-19 patients, the expression levels of resistin were high in SF, but leptin and adiponectin are both low." (PMID 39469144, 2024).